AFF1 (ALF transcription elongation factor 1)
Diseases named in the same sentence as AFF1 in open-access papers (continued):
Sharing a sentence is not in itself a finding about the gene and the disease.
cataract (1 paper, 2012). Partial or complete opacity of the crystalline lens of one or both eyes that decreases visual acuity and eventually results in blindness. "Of these genes, only AFF1 has a known association with cataracts." (PMID 22690116, 2012).
HIV-1 infection (1 paper, 2024). The type species of lentivirus and the etiologic agent of acquired immunodeficiency syndrome (AIDS). "However, knock-out of the other SEC components either did not alter HIV-1 infection (AFF4, ELL2, AF9) or resulted in a very slight, but statistically significant increase in infection (AFF1, ENL)." (PMID 39259751, 2024).
liver disease (1 paper, 2025). "For example, (+)-chelidonine, identified in our docking screen as a top candidate, has demonstrated anti-inflammatory and anti-proliferative activities in previous cell-based models, but its affinity for AFF1 and efficacy in liver disease contexts are untested." (PMID 40823550, 2025).
pancreatic cancer (1 paper, 2023). "The expression of AFF1-4 in PDAC tissues consistently displayed a higher level than those in normal tissues, suggesting the members of AF4/FMR2 family would exert the progressive function for pancreatic cancer." (PMID 37063434, 2023).
sarcoma (1 paper, 2022). A usually aggressive malignant neoplasm of the soft tissue or bone. "At present, no studies have clearly pointed out the relationship between AFF1 methylation and OS (HG) or CHORD, but some studies have reported that the expression of CD133 in these two types of sarcomas changes specifically, which may serve as a potential therapeutic target." (PMID 36619306, 2022).
cancer (32 papers, 2007 to 2025). A tumor composed of atypical neoplastic, often pleomorphic cells that invade other tissues. "After multivariate cox’s model filtering, we identified 4 mRNAs (MLLT3, CEBPA, HIST2H3C and AFF1) in ‘Transcriptional misregulation in cancer’ pathway were independently associated with prognosis." (PMID 30181715, 2018). "Formation of an SEC with AFF1 or AFF4 is a primary control factor in cancer pathogenesis and development." (PMID 32606293, 2020). "In that work, AFF1 rs17703261 was inversely associated with cancer risk (OR for the A/T was 0.34 95% CI 0.20, 0.58) and KIAA0423 rs1053667 was directly associated with cancer risk (OR for the C/T was 3.29 95% CI 1.72, 6.32)." (PMID 26630397, 2015). "In order to explore the possible functions of AFF1 in solid tumors, we first investigated whether AFF1 expression level correlates with the overall clinic outcomes of different cancers." (PMID 33493519, 2021). "PROM1 encodes a transmembrane glycoprotein (i.e., CD133) commonly regarded as a cancer stem cell marker and reported to be an important target of KMT2A::AFF1." (PMID 37740239, 2023). "Overall, our data show that enhancer heterogeneity is highly prevalent in KMT2A::AFF1 ALL and may be a mechanism that drives transcriptional heterogeneity in cancer more generally." (PMID 40729681, 2025). "We identified HBV integrations with high integration allele fractions in tumors in seven non-recurrent cancer-related genes, including GAS7, NSP, RSPO2, NRG1, PRDM16, ARID1B, and AFF1." (PMID 33557409, 2021). "Among nine cancer-associated mutations that determine sensitivity to ATRA (Notch 1, BCR_ABL, KIT, FLT3, APC, TET2, K-ras, ALK, MLL_AFF1), KRAS, APC, and KIT mutations are associated with resistance to ATRA (only K-ras is shown)." (PMID 23982413, 2013). "However, the KEGG pathway “Transcriptional misregulation in cancer” were represented with four genes mapping to the pathway (Bcl6, Zbtb16, Aff1, and Dusp6), but not significant (adj." (PMID 34428250, 2021). "However, the role of AFF1 solid tumor specifically in SEOC is not clear thus extensive work to elucidate the mechanisms of miR-31 and AFF1 binding interaction in this cancer shall follow." (PMID 26260454, 2015).
tumor (20 papers, 2011 to 2025). "Interestingly, expression of most of the fusion partners including the high‐frequency partners like AFF1, MLLT1, MLLT3, MLLT10, ELL, and MLLT4, were positively correlated with MLL1 expression irrespective of the tumor type." (PMID 30548174, 2019).
infection (3 papers, 2023 to 2024). The state of being infected such as from the introduction of a foreign agent such as serum, vaccine, antigenic substance or organism. "This is consistent with our data, as we see a reduction of infection for both LAI and Q23BG505 in AFF1 KO Jurkat cells." (PMID 36744886, 2023).
hematologic cancers (1 paper, 2025). "Functionally, AFF1 has been implicated in modulating transcriptional elongation, mRNA processing, and cellular responses to external stimuli, suggesting broader roles in health and disease beyond hematologic cancers." (PMID 40823550, 2025).
AFF1 also shares sentences with these, for which no sentence is quoted: myeloid leukemia (6 papers); B-cell acute lymphoblastic leukemia (5); B-cell lymphoma (5); breast carcinoma (4); autoimmune disease (3); Down syndrome (2); head and neck squamous cell carcinoma (2); Intellectual disability (2); Multiple myeloma (2); myeloid sarcoma (2); rheumatoid arthritis (2); Splenomegaly (2); T-cell ALL (2); type 2 diabetes (2); virus infection (2); adenoma (1); alveolar rhabdomyosarcoma (1); B cell acute lymphoblastic leukaemia (1); B-cell neoplasm (1); bladder cancer (1); blood cancer (1); brain ependymoma (1); brain injury (1); Burkitt lymphoma (1); cardiomyopathy (1); central nervous system leukemia (1); childhood leukemia (1); chordoma (1); chronic kidney disease (1); colon adenocarcinoma (1).
A further 26 diseases each share a sentence with AFF1 in 1 paper.